KIF2C (kinesin family member 2C)
Diseases named in the same sentence as KIF2C in open-access papers (continued):
Sharing a sentence is not in itself a finding about the gene and the disease.
pancreatic adenocarcinoma (1 paper, 2024). "Interestingly, 1.8% of all patients in the TCGA cohort including PAAD (Pancreatic Adenocarcinoma) had genetic alterations in the KIF2C gene, which included predominantly missense mutations or amplifications." (PMID 38344808, 2024).
prostate adenocarcinoma (1 paper, 2022). "Using the TCGA prostate adenocarcinoma (PRAD) dataset, patients were divided into high and low expression groups based on the median value of KIF2C expression to see if there was an association between KIF2C expression and PCa clinicopathological features." (PMID 35720323, 2022).
prostate tumor (1 paper, 2023). "Other kinesin superfamily proteins, such as KIF2C or KIF3A are associated with prostate tumor progression." (PMID 34593983, 2023).
pulmonary embolism (1 paper, 2021). The obstruction of the pulmonary artery or one of its branches by an embolus, sometimes associated with infarction of the lung. "Two and three nude mice in KIF2C-knockdown SK-Hep1 and the corresponding control groups died from pulmonary embolism by accident, respectively, and no mice in other groups died from pulmonary embolism." (PMID 32748349, 2021).
rectal cancer (1 paper, 2021). A primary or metastatic malignant neoplasm that affects the rectum. "The prognostic index formula for colon and rectal cancer patients in the training cohorts was as follows: Risk score = [Status of PARPBP ∗ (-0.6921)] + [Status of KNSTRN ∗ (1.4204)] + [Status of KIF2C ∗ (-0.9696)]." (PMID 34568334, 2021).
renal carcinoma (1 paper, 2021). A carcinoma arising from the epithelium of the renal parenchyma or the renal pelvis. "In an independent study conducted in renal cancer cells, ATIP3 was found to regulate the phosphorylation of KIF2C (also designated MCAK), another microtubule depolymerizing kinesin of the KinI family." (PMID 34062782, 2021).
sarcoma (1 paper, 2019). A usually aggressive malignant neoplasm of the soft tissue or bone. "Amongst the eight remaining hub genes, CDC20, CCNB2, AURKB, MAD2L1, CENPE, KIF2C, and PCNA were highly expressed and related with negative prognosis of sarcoma." (PMID 31870357, 2019).
Sepsis (1 paper, 2023). Sepsis is defined as life-threatening organ dysfunction caused by a dysregulated host response to infection. "In our investigation, we identified GTPBP2, ALDOA, PRKAR2A, NHLRC2, and KIF2C as genes related to sepsis death using three distinct techniques." (PMID 38054005, 2023). "In our study, we constructed a machine learning model using five genes, including GTPBP2, ALDOA, PRKAR2A, KIF2C, and NHLRC2, to identify sepsis patients with a poor prognosis." (PMID 38054005, 2023).
squamous carcinoma (1 paper, 2023). "KIF2C affects biologically malignant behaviors of NSCLC cellsWith the popularization of computed tomography and other imaging screening methods, adenocarcinoma incidence has increased significantly and has surpassed squamous carcinoma as the most common type." (PMID 37142638, 2023).
testicular germ cell tumor (1 paper, 2025). A germ cell tumor arising from the testis. "Based on the TCGA TARGET GTEx pan‐cancer dataset, we found KIF2C mRNA expression levels to be significantly upregulated in 33 malignant tumors but downregulated in TGCT (Testicular Germ Cell Tumors)." (PMID 40292920, 2025).
testis cancer (1 paper, 2021). "We found KIF2C might work in the testis cancer and spermatogenesis." (PMID 34591790, 2021).
vascular tumour (1 paper, 2022). "The KPNA2, LPCAT1, KIF2C, and SPP2 genes were statistically correlated with pathological stage, histologic grade, ECOG, vascular tumour cell type, and tumour status." (PMID 35915607, 2022).
cancer (85 papers, 2007 to 2025). A tumor composed of atypical neoplastic, often pleomorphic cells that invade other tissues. "Studies have linked abnormal KIF2C expression to erroneous chromosome aggregation and separation, which can lead to changes in cell genotype and potentially cause uncontrolled cancer cell proliferation." (PMID 40292920, 2025). "High KIF2C expression has been linked to the hallmarks of cancer, including genome instability, resistance to cell death, activation of invasion and metastasis, immune evasion, and the avoidance of cellular senescence." (PMID 40292920, 2025). "Dysregulation of KIF2C can lead to abnormal chromosome segregation, resulting in aneuploidy and polyploidy, which are frequently observed in various cancers and are associated with poor prognosis." (PMID 40292920, 2025). "It is therefore hardly surprising that KIF2C has been linked to MT dynamics during interphase, polarization of ECs, assembly and disassembly of FAs and migration/invasion of cancer as well as benign cells." (PMID 38344808, 2024). "All meta-analyses showed poor prognosis for cancer patients with KIF2Chigh expression, associated with a decreased overall survival and reduced disease-free survival, indicating KIF2C’s oncogenic potential in malignant progression and as a prognostic marker." (PMID 38344808, 2024). "Yet, an important and less studied aspect is the involvement of KIF2C in immune responses, where the role of KIF2C in immune cell infiltration leading to tumor inhibition is either positively or negatively associated, depending on the cancer type." (PMID 39268460, 2024). "In sum, all of these studies point to the notion that KIF2C is associated with increased cancer malignancy in diverse cancer entities." (PMID 38344808, 2024). "Overall, our study strongly suggests that B-Myb and its critical target gene KIF2C are promising diagnostic and therapeutic targets for cancers including LUAD." (PMID 39309447, 2024). "These modern tools and techniques will help to confirm that KIF2C can serve as a diagnostic and prognostic marker for patients with various cancers." (PMID 38344808, 2024). "Cell cycle regulating proteins such as CDCA4, CDCA8, and KIF2C have been linked to tumor growth and progression, affecting the proliferation, migration, invasion and metastasis of cancer cell lines." (PMID 38605349, 2024). "Under the microscope, it was observed that, for both the ASPC-1 and MIA-PaCa2 cell lines, the interference of KIF2C caused a distinct decrease in the ability of cancer cells to invade and migrate." (PMID 36900292, 2023). "KIF2C is frequently up-regulated in multiple types of cancer and is associated with cancer development." (PMID 37016301, 2023). "The results of our pan-cancer analysis indicated that KIF2C had different degrees of genetic variation in 26 cancer types, including mutations, structural variants, amplification, and deep deletion." (PMID 35720323, 2022). "With respect to KIF2C, changes in expression have been linked to a poor prognosis for cancer recovery in several studies." (PMID 35720323, 2022). "In summary, the results of this pan-cancer analysis showed that the abnormal expression of KIF2C was associated with poor prognosis of different cancer types." (PMID 35153749, 2021). "As a clear association between KIF-2C expression and cancer progression has been observed in this and previous studies, KIF-2C can be considered as an attractive target for immunotherapy." (PMID 27563815, 2016). "Given the known association between KIF2C expression and aggressive tumor characteristics including increased cell proliferation and metastasis, its role in cancer progression has been extensively studied in other malignancies such as glioma, colorectal cancer, and prostate cancer." (PMID 40292920, 2025).
cancer (continued). "Overall, the functional analysis indicated that esketamine suppressed ERCC6L, AHR and KIF2C may be the underlying mechanisms for its anti-cancer effects, although further study is needed." (PMID 37968758, 2023). "Additionally, we used EPIC, CIBERSORT-ABS, and QUANTISEQ algorithms to analyze the correlation of KIF2C with cancer-associated fibroblasts, M2 macrophages, and Tregs in KIRC, LGG, LIHC, and THYM." (PMID 35685442, 2022). "In addition, our pan-cancer analysis of the prognostic indicated that KIF2C was significantly associated with poor prognosis in different tumor types and was a high-risk factor affecting tumor prognosis." (PMID 35720323, 2022). "KIF2C is upregulated in some cancer tissues and is associated with resistance to chemotherapy." (PMID 34663310, 2021). "Moreover, high expression levels of KIF2C were associated with the poor prognosis of most cancers, which strongly suggested that KIF2C was a potential prognostic biomarker for tumor treatment." (PMID 35153749, 2021). "(2014) identified KIF2C as a novel FOXM1 transcriptional target that may be implicated in the acquisition of chemoresistance in cancer treatment." (PMID 31579605, 2019). "Finally, we aimed to evaluate the therapeutic and diagnostic values of KIF2C in cancers." (PMID 39309447, 2024). "Therefore, abnormal expression of KIF2C could theoretically contribute to the development of cancer by causing mitotic anomalies, chromosomal instability, and uncontrolled transcription." (PMID 37717078, 2023). "In this work, we investigated the prognosis of KIF2C in pan-cancer and its relationship with immune infiltration, and found that KIF2C was associated with cell cycle after enrichment analysis, and finally, we investigated the correlation between KIF2C expression and anticancer drug sensitivity." (PMID 35685442, 2022). "As an initial step, TCGA pan-cancer transcriptomic data were mined to characterize the expression landscape of KIF2C and its potential implications in LUAD." (PMID 41341805, 2025). "Aberrant expression of KIF2C has been observed in various cancers, including breast, lung, gastric, and prostate tumors." (PMID 40433108, 2025). "For other genes, the proportion changes in different cell types expressing BIRC5, CDK1, AURKA, E2F1, and KIF2C are remarkably similar to the overall proportion changes in different cell types during cancer progression." (PMID 39859485, 2025). "Western blot experiments confirmed the reduced expression of CDK1, CCNB1, and PLK1 in KIF2C knockdown cancer cells at the protein level." (PMID 41333555, 2025). "The analysis demonstrated that KIF2C was markedly upregulated in multiple cancer types, with particularly strong elevation observed in LUAD." (PMID 41341805, 2025). "Recent studies have confirmed that KIF2C/MCAK plays a pivotal role in cancer progression, particularly by modulating critical cellular processes like migration, invasion, DNA repair, and immune modulation." (PMID 40292920, 2025). "Our results highly suggest the critical implication of B-Myb-mediated gene regulation in cancers, and the promising therapeutic and prognostic potentials of B-Myb and KIF2C for cancer diagnosis and treatment." (PMID 39309447, 2024). "Overall, the results highly suggest that KIF2C serves as a promising therapeutic target for various types of cancers including LUAD." (PMID 39309447, 2024). "In line, we have reviewed its expression in various cancer entities and discussed its potential clinical significance, including a meta-analysis correlating KIF2C’s expression with the OS of BC, NSCLC and HCC patients." (PMID 38344808, 2024). "In fact, several studies showed that depletion or knockdown of KIF2C interferes with proliferation, migration and invasion capacity of cancer cells." (PMID 38344808, 2024).
cancer (continued). "The prognostic evaluation of KIF2C in TCGA cancer cohorts revealed that the expression level of KIF2C was significantly correlated with the overall survival rate of the patients with ACC, KIRC, KIRP, LGG, LIHC, LUAD, MESO, and PAAD." (PMID 39309447, 2024). "This was followed by a systematic search of KIF2C/MCAK’s expression in various malignant tumor entities and its correlation with clinicopathologic features." (PMID 38344808, 2024). "In summary, these observations clearly support the concept that KIF2C is involved in at least five different hallmarks of cancer, suggesting a possible role in tumor development, progression and malignancy." (PMID 38344808, 2024). "Overall, our results highly suggest the critical implication of B-Myb-mediated gene regulation in cancers, and the promising therapeutic and prognostic potentials of B-Myb and KIF2C for cancer diagnosis and treatment." (PMID 39309447, 2024). "In this study, we have discovered a critical interaction between KIF2C and Nek2A that regulates centrosome clustering in cancer cells, marking the first identification of such a relationship." (PMID 38493150, 2024). "Intriguingly, analysis of cancer patient datasets revealed a strong correlation between the expressions of Nek2A and KIF2C (Spearman: 0.75, Pearson: 0.79, R2: 0.62), suggesting a possible interaction between these proteins." (PMID 38493150, 2024). "KIF2C is involved in regulating cell mitosis and the repair of double-strand DNA breaks in cancer cells." (PMID 39458936, 2024). "KATNA1, STMN1 and KIF2C are key proteins involved in microtubule dynamics, with implications in cancer progression and potential targets for anticancer drug development." (PMID 39175104, 2024). "Altogether, our findings indicate that KIF2C is essential for cancer cell growth and cell cycle progression." (PMID 39309447, 2024). "Pan-cancer transcriptomic analysis revealed that the overexpression of both B-Myb and KIF2C presents as independent prognostic markers in various types of cancer." (PMID 39309447, 2024). "Both phosphorylation and dephosphorylation of this site affect the catalytic activity of human KIF2C in cancer and normal cells." (PMID 38344808, 2024). "Discovering partners such as KIF2C offers fresh insights into cancer biology and new possibilities for targeted treatment." (PMID 38493150, 2024). "Upregulation of KIF2C in CIN-positive cancer cells was found to increase microtubule turnover to counteract the hyperstable kinetochore-microtubule attachments that lead to lagging chromosomes." (PMID 38177531, 2024). "Our study reveals a novel interaction between Nek2A and KIF2C in cancer cells with centrosome amplification, suggesting a coordinated regulation to maintain centrosome clustering." (PMID 38493150, 2024). "In summary, these data illustrate how KIF2C’s increased and decreased expression in cancer cells is able to fuel tumorigenesis." (PMID 38344808, 2024). "This work delineated the promising research perspective of KIF2C with modern in vivo and in vitro technologies to further decipher the function of KIF2C in malignant tumor development and progression." (PMID 38344808, 2024). "The data show that the gene expression of KIF2C is significantly increased in at least 33 different cancer types compared to benign tissue." (PMID 38344808, 2024). "Specifically, we found that KIF2C is indispensable for the prevention of clustering, triggered by Nek2A, a phenomenon exclusive to cancer cells with supernumerary centrosomes." (PMID 38493150, 2024). "This study highlights the potential of targeting Nek2A and its interactors, like KIF2C, for novel cancer therapies aimed at managing centrosome-related genomic instability." (PMID 38493150, 2024). "The overexpression of KIF2C in many cancers has led to proliferation, EMT activation, invasion, and metastasis via PI3K/AKT, mTORC1, and MAPK/ERK signaling." (PMID 39268460, 2024).
cancer (continued). "KIF2C is a critical regulator of cancer cell growth and mitosis, and maintains high cancer cell motility ability and microtubule dynamics." (PMID 39309447, 2024). "We then systematically compared the expression level of KIF2C between normal and tumor tissues using TCGA pan-cancer transcriptomic data." (PMID 39309447, 2024). "After that, we also extracted proteins from cancer and adjacent tissues and detected the expression of KIF2C by Western blot." (PMID 36900292, 2023). "We intuitively found that the expression of KIF2C in cancer tissue was higher than that in adjacent tissue." (PMID 36900292, 2023). "In other words, the expression of KIF2C in normal pancreatic tissue is low, but after normal tissue develops into cancer, its expression increases rapidly." (PMID 36900292, 2023). "The aim of this study was to clarify the ability of KIF2C to enhance cancer cell viability, proliferation and invasion in NSCLC by activating the AKT-GSK3β-β-catenin pathway." (PMID 37142638, 2023). "The results of the TCGA analysis indicated that the expression of KIF2C was different in various cancers." (PMID 36900292, 2023). "Cancer cell proliferation, migration and invasion are a significant part of cancer progression, so we investigated the effect of KIF2C on these features in NSCLC by performing transwell, colony formation and wound healing assays." (PMID 37142638, 2023). "The evidence presented thus far supports the idea that KIF2C is closely related to the occurrence of cancer." (PMID 36900292, 2023). "Previous studies have identified that KIF2C was overexpressed in some cancers and facilitates the growth and invasion of tumor cells." (PMID 35685442, 2022). "KIF2C is upregulated in endometrial cancer (EC), which can cause a malignant phenotype in EC and negatively correlates with CD8T cells, which have cancer suppressive effects." (PMID 35685442, 2022). "Using the cBioPortal (TCGA, Pan-Cancer Atlas) database, the pan-cancer alterations of KIF2C were investigated." (PMID 35720323, 2022). "In previous research, Kinesin family member 2C (KIF2C), as an oncogene, has been demonstrated to have a key role in the incidence and progression of different cancers." (PMID 35720323, 2022). "To explore the relationship between KIF2C and immunotherapy, we performed a pan-cancer correlation analysis of KIF2C with 47 immune checkpoint (ICP) genes." (PMID 35685442, 2022). "We investigated the prognostic value of KIF2C in TCGA pan-cancer by univariate Cox regression analysis." (PMID 35685442, 2022). "The results of our pan-cancer analysis indicated that KIF2C was highly expressed in 28 tumors, including PCa, which was consistent with previous results reported in the literature." (PMID 35720323, 2022). "We calculated the levels of correlation between KIF2C and promoter methylation in 33 types of cancer using cBioPortal web-based data sets." (PMID 35720323, 2022). "We also used the ESTIMATE algorithm to produce immune cell scores, estimate scores, and tumor purity in 33 different types of cancer, and looked at the relationship between KIF2C expression levels and these three scores." (PMID 35720323, 2022). "In the pan-cancer dataset, we calculated the relationship between KIF2C expression and patient prognosis." (PMID 35720323, 2022). "On the basis of the ImmuCellAI database, we then did a pan-cancer analysis of the connection between KIF2C expression and 24 types of invading immune cells in 32 cancer types using the CIBERSORT approach." (PMID 35720323, 2022). "Using the TIMER database, we examined the correlation between KIF2C expression and immune infiltration levels in various cancers." (PMID 35685442, 2022). "Comparisons of KIF2C expression between normal tissues and tumor samples across 33 types of cancers showed strikingly upregulated KIF2C expression among 28 types of tumor tissues." (PMID 35720323, 2022).